TNC (tenascin C)
Diseases named in the same sentence as TNC in open-access papers (continued):
Sharing a sentence is not in itself a finding about the gene and the disease.
cancer (continued). "TTA-1 aptamer binds specifically to tenascin-C, an extracellular matrix protein overexpressed in cancer cells." (PMID 25871725, 2015). "In this study, simultaneous imaging of the cancer biomarkers, tenascin-C and nucleolin, was performed using two types of aptamer-conjugated QDs." (PMID 25871725, 2015). "Cancer cells are an important source of ECM in cancer tissue and deposit a significant amount collagen, fibronectin, and tenascin-C." (PMID 26682273, 2015). "Of specific interest is the induction of TPM1, TPM2, TNC and POSTN, suggesting a fundamental reprogramming of lung fibroblasts such that the cells exhibit a gene expression profile that is typical for carcinoma-associated fibroblasts." (PMID 25924783, 2015). "Our group has recently reported promising examples of therapeutic activity in cancer patients for anti-tenascin-C antibodies, armed with interleukin-2 or with iodine-131." (PMID 24950200, 2014). "The source of tenascin-C can be the tumor cells themselves as well as the stromal cells of the cancer microenvironment." (PMID 24495796, 2014). "Tenascin-C (TNC) is a typical matricellular protein, which is highly expressed during embryonic development, wound healing, inflammation, and cancer invasion." (PMID 25120494, 2014). "By contrast, large tenascin-C isoforms can be very abundant during embryogenesis, in cancer and in chronic inflammation." (PMID 24950200, 2014). "By enhancing Wnt and Notch signaling in cancer cells, Postn and tenascin C provide physical and signaling support for metastasis-initiating cells." (PMID 22966238, 2012). "TNC, the best-described family member, reappears during pathological conditions such as cancer, inflammation or wound-healing." (PMID 22947174, 2012). "Sulfatide is a glycosphingolipid known to interact with several extracellular matrix proteins, such as tenascin-C which is overexpressed in many types of cancer including that of the colon." (PMID 23145140, 2012). "Several matricellular proteins, such as SPARC, OPN, CCN1, CCN6, and TNC, have been implicated in either the promotion or suppression of EMT, highlighting their role in cancer progression and malignant behavior of cancer cells." (PMID 22481923, 2012). "In human pancreatic tissues, TNC expression increases in the progression from low-grade precursor lesions to invasive cancer." (PMID 21747918, 2011). "A similar phenomenon was reported previously; i.e., that tenascin-C is specifically expressed at the invasive fronts of cancers, where neoplastic cells acquire a migratory characteristic during EMT." (PMID 20664686, 2010). "Moreover, researchers have found significant differences in metabolites like Tenascin C (TNC) and Apolipoprotein A1V (Apo-AIV) in the serum of PCa patients, suggesting a strong association with cancer metastasis and prognosis." (PMID 40681942, 2025). "This implies a possible role of Tenascin C in cancer invasion." (PMID 41009413, 2025). "Moreover, studies across various cancers identified N-cadherin, Tenascin-C, P-cadherin, NFATc, NR2F, PDPN and LAMC2 as drivers of the p-EMT state." (PMID 40764669, 2025). "TNC interacts with multiple receptors through its unique six-armed structure, influencing biological processes, such as cell adhesion, migration, and proliferation, thereby playing a significant role in cancer initiation and progression." (PMID 40046232, 2025). "The ability of TNC to modulate Wnt signaling across a variety of cancers could lead to the development of target therapies both for TNC and Wnt." (PMID 39951495, 2025). "CAFs may also act indirectly by overproducing ECM components such as fibronectin, collagen, hyaluronic acid, and tenascin-C, increasing cancer cell proliferation and invasion, leading to metastasis." (PMID 40136652, 2025). "Moreover, HLA-E-positive cancer cells interacted with mesothelial cells via various cell-matrix proteins, including collagen and TNC (sFigure 6B)." (PMID 40959273, 2025).
cancer (continued). "Tenascin-C is an extracellular matrix glycoprotein involved in various physiological and pathological processes, including tissue development, wound healing, inflammation, and cancer progression." (PMID 40699873, 2025). "The observed anticancer polarization of these cancer-associated fibroblasts in response to treatment may be related to a reduction in CCL2, TNC, MMP9 and MMP-2." (PMID 41009006, 2025). "Importantly, cancer-derived exosomes that express high levels of tenascin-C on their surface transfer this protein to T lymphocytes and reduce mTOR signaling through interactions with α5β1 and αvβ6 integrins on T cells." (PMID 41294803, 2025). "TNC is an extracellular matrix (ECM) protein that is upregulated in many types of cancer." (PMID 37759229, 2023). "Tenascin-C is involved in phenotypic control of fibroblasts elsewhere—it acts with Twist1 transcription factor signalling to stably, but reversibly, activate fibroblasts in wound healing and permanently in fibrotic pathology and cancer." (PMID 36834965, 2023). "Extending the application of this assay to other diseases, including different autoimmune conditions, fibrosis, and cancer, will also enable a better understanding of the complex patterns of expression of tenascin-C and provide new insight into the inflammatory status across a wider pathology." (PMID 38077374, 2023). "TNC mRNA has been detected both in stromal as well as in cancer cells." (PMID 35785162, 2022). "Certain splice isoforms of tenascin-C were found in particular types of cancer." (PMID 35008401, 2022). "Therefore, understanding the role of TNC in cancers and stem cells can contribute to the development of new therapeutic avenues." (PMID 36033448, 2022). "Of note, this model with inducible TNC overexpression could be highly valuable for addressing the roles of high TNC in cancer progression." (PMID 36102918, 2022). "However, in cancer, TNC is highly expressed around blood vessels, in immune suppressive matrix niches, at the invasive front and in metastases." (PMID 36102918, 2022). "Overall, these findings indicate that TNC may play a crucial role in promoting cancer growth, suggesting it as an interesting target for future functional studies, especially in lung SCC." (PMID 36289644, 2022). "Taken together, the multiple levels by which TNC regulates these pathways might reflect the importance of TNC in normal tissue and immune homeostasis, which becomes out of control in cancer." (PMID 36102918, 2022). "myCAFs may also express other matrix proteins including THBS1 (thrombospondin 1), THBS2, and TNC (tenascin C, a matrix protein), to communicate with immunocytes, smooth muscle cells, cancer cells, and plasma cells through CD44, integrin (α3β1), and SDC1." (PMID 35986392, 2022). "Overexpression of tenascin C stimulates migration of cancer cells." (PMID 34462873, 2022). "However, studies show that expression of TNC by reactive fibroblasts occurs at late time points and thus, in early metastasis, cancer cells are the primary source of TNC35." (PMID 35469015, 2022). "TNC may be involved in cancer growth and metastatic processes via the Hedgehog (HH) signaling pathway, caused either by mutations in the pathway (ligand independent) or through HH overexpression (ligand dependent)." (PMID 34490089, 2021). "However, upregulation of TNC has been found in wound healing, cancer development, and cardiovascular disease, where expression levels of TNC appear to be a reliable indicator of disease progression and poor prognosis." (PMID 34492130, 2021). "Although the overall metabolism in cancer is altered as compared to healthy tissue, TnC could have clinically relevant role for ECM mechanical properties in cancer." (PMID 34072323, 2021).
cancer (continued). "VEGF-A and Tenascin-C are other relevant markers in context of stromal contribution to cancer progression; the expression of the former is a driver of angiogenesis and metastatic colonization, while that of the latter provides cancer cells protection from apoptosis." (PMID 34646829, 2021). "This suggests that cancer cells may be able to hijack important immune-related functions of tenascin-C in tumors." (PMID 33912190, 2021). "In cancer, TnC and other ECM components undergo an important interplay." (PMID 34072323, 2021). "Moreover, cancer cells are able to educate fibroblasts to produce periostin and Tenascin C (TNC), enhancing metastatic colonization of the lung." (PMID 34201840, 2021). "Since the first discovery regarding the role of TNC in cancers, over two decades have passed." (PMID 33876384, 2021). "Accumulating evidence has shown diverse and important roles for TNC in responses to injury as well as cancer stroma, particularly in the regulation of inflammation; however, neither the knockout nor overexpression of TNC induces a distinct phenotype during heart development." (PMID 34072423, 2021). "Finally, we sought to determine the effects of cancer EVs on tenascin-C expression in fibroblasts in vitro." (PMID 34564696, 2021). "Moreover, SMOC1 was identified as a new cancer-related protein by interacting with tenascin-c, which was an ECM protein and was highly expressed in many human cancers." (PMID 34869577, 2021). "Thus, TNC down-regulation seems to enhances the adhesiveness of cancer cells, showing the direct involvement of TNC in cell adhesive properties." (PMID 32817625, 2020). "Our results show that down regulation of TNC reverses the malignant phenotype of the cancer cells." (PMID 32817625, 2020). "It seems likely that, down-regulation of TNC mRNA may be a unique approach to sensitizing cancer cells with S-phase chemotherapy." (PMID 32817625, 2020). "Despite high expression of tenascin-C in malignant tumors and a correlation with poor prognosis, the main role of tenascin-C in the pathogenesis of cancer remains unclear." (PMID 31261783, 2019). "ECM significantly influences not only tumour growth, but also migration of cancer cells and metastatic spread via production of numerous types of collagens and noncollagenous proteins such as tenascin-C, different variants of fibronectin and proteoglycans." (PMID 30925774, 2019). "Future studies may reveal whether the same mechanism also applies when SPP1 and TNC are produced by the cancer stroma." (PMID 30190333, 2018). "With regard to the CAF model, patient-derived normal and according cancer-associated fibroblasts revealed a conserved gene expression, defined by increased transcript levels of ACTA2, COL1A1, TNC, VEGFA and ALDH1A3, with concomitant decreased expression of CAV1, CD44 and VIM in CAFs." (PMID 28372546, 2017). "Cancer-associated fibroblasts (CAFs), identified by intracellular α-SMA, are known predictors of poor prognosis in various malignancies with highly similar staining pattern as tenascin-C and fibronectin." (PMID 28978001, 2017). "However, re-expression of tenascin-C occurs in injured tissues and in pathological remodeling in various diseases, such as cancer." (PMID 28978001, 2017). "Aptamer TTA1 was selected to bind the extracellular matrix protein, tenascin-C, of cancer cells." (PMID 27973403, 2016). "However, in adults Tenascin-C and -W are expressed only in pathophysiological conditions such as cancer development." (PMID 26967391, 2016). "Moreover, Tenascin-C overexpression in cancer cells and stromal fibroblasts was an independent poor prognostic factor for overall survival (OS) and disease-free survival (DFS)." (PMID 26731558, 2016). "Tenascin-C staining was particularly evident at the cancer cell invasive front." (PMID 26731558, 2016).
cancer (continued). "Several isoforms of Tenascin-C are formed by alternative splicing and it was reported that especially its large isoform plays a decisive role in the regulation of angiogenesis and in tumorigenesis of cancer." (PMID 26967391, 2016). "Similarly, RBM47-induced splicing changes were seen in genes such as SLK, MDM4 and TNC, all of which are genes with known functions in cancer." (PMID 24898756, 2014). "However, TNC expression is up regulated in pathological situations involving tissue injury, wound healing, inflammation and cancer." (PMID 24467805, 2014). "Similarly, Tenascin C and MTA1 which are also associated with invasion and migration of cancer cells were upregulated in 3D vs. 2D 293T cells." (PMID 20615238, 2010). "Indeed, Masson-Trichrome and picrosirius red staining showed high levels of collagens adjacent to the carcinomas and immunohistochemistry validated increased levels of Laminin β1, Laminin γ1, Fibronectin, Periostin and Tenascin C, most of which showed a discrete pattern adjacent to the carcinomas." (PMID 39953252, 2025). "For example, tenascin-C is a pro-inflammatory extracellular matrix protein that exhibits restricted expression in healthy adult tissues but has long been known to be significantly and persistently upregulated in autoimmune, fibrotic, and metabolic diseases, as well as in cancer." (PMID 38077374, 2023). "Furthermore, previous explorations have identified that tenascin-C (TNC) interacts with syndecan-4 and blocks integrin/syndecan complex to mediates cell-fibronectin adhesion, which sustains proliferation and induces angiogenesis in cancer." (PMID 36906534, 2023). "Moreover, cancer progression is also worth evaluating following collagen and TNC knock-down." (PMID 36289644, 2022). "Hence, a more detailed study may be required to clarify the role of TNC in cancer-related inflammation." (PMID 36033448, 2022). "In addition, TnC was found to be expressed de novo in lesions and during wound healing, but also in pathological conditions, such as inflammation, cancer and trauma." (PMID 33996833, 2021). "Furthermore, various studies explored Tenascin-C as trigger for cancer drug resistance." (PMID 32560557, 2020). "Expression of TNC in cancer cells might be a potential prognostic biomarker in patients with CRC." (PMID 32322169, 2020). "Additionally, it has been reported secretion of tenascin-C by human carcinoma cell lines." (PMID 29515769, 2018). "By expressing tenascin-C, the cancer cells may support their own ability to metastasize." (PMID 28978001, 2017). "Therefore, activation of TNC/integrin receptor-mediated signalling may be a putative target in cancer treatment." (PMID 28415821, 2017). "Moreover, Tenascin-C could be a novel therapeutic marker for selective targeting of stromal fibroblasts and cancer cells in ESCC." (PMID 26731558, 2016). "In addition to fibronectin, fibroblasts express Tenascin-C (TN-C) glycoprotein, within the premetastatic site, which may protect the cancer cells from apoptosis." (PMID 27092178, 2016). "It is interesting to note that the ECM glycoproteins fibronectin, tenascin-C and periostin, that were found here among the most highly up-regulated genes during the angiogenic switch, have also been identified as crucial for metastatic colonization in other cancer models in vivo." (PMID 25301723, 2014). "TNC plays an active role in development, nerve growth, cancer, and wound healing, and thus may be involved in the regulation and signaling of growth factors to control cell proliferation and differentiation, as well as signaling directly through its multiple integrin binding domains." (PMID 23637968, 2013). "The expression of TNC is frequently found in circulating cancer cells isolated from the pleural effusion of patients with systemic breast cancer, suggesting that cancer cell autonomy in TNC production may have a role in the broad and efficient spread of the disease." (PMID 22405133, 2012).
cancer (continued). "PSCs also secrete Wnt and tenascin C (TnC), which activate the oncogenic signaling pathways of β-catenin and YAP/TAZ, promoting cancer cell survival." (PMID 40136652, 2025). "TNC is an important matricellular ECM protein involved in development and morphogenetic events such as inflammation, injury repair or cancer." (PMID 36829478, 2023). "OPN, TnC, and POSTN significantly stimulated cell motility and the cancer-stem-cell-like phenotype in HuCCT-1 (human iCCA cell line)." (PMID 36902188, 2023). "Biomarkers (FAP, POSTN, PDGFRα/β, FSP-1, CD90, Palladin, OPN, AEBP1, TNC, CD10, and GPR77) represent cancer-promoting CAFs." (PMID 37476379, 2023). "In multiple cancer cells, researchers have identified thousands of OCT3/4 target genes involved in critical tumorigenesis pathway, such as PTEN signaling, TNC (metastasis) and MMP2(invasiveness)." (PMID 37476834, 2023). "The glycoprotein tenascin-C (TNC) is an ECM molecule that plays multiple and context-dependent roles in cancer that have been comprehensively reviewed elsewhere." (PMID 36102918, 2022). "Unlike the lung-derived CD44high groups, lungL1 and lungL2 cells retained properties of stem cells but dramatically increased their expression of mesenchymal-like signaling pathways involved in cancer cell maintenance and dormancy (TSP, TNC, BMP)." (PMID 34579762, 2021). "Tenascin C (TNC) is a glycoprotein of ECM overexpressed during normal tissue repair and in many malignant tumors." (PMID 35047971, 2021). "In conclusion, this work highlights a new role for TNC, representing a newly discovered link between MET-expressing cancer cells and the stroma compartment." (PMID 34298732, 2021). "The downregulated genes TNC and MMP1 are known to be commonly induced in cancer, the same is true for PMP2 and CDH2." (PMID 34439267, 2021). "Tenascin-C, a300 kDa large glycoprotein, is overexpressed within the ECM of numerous cancer cells such as breast, colon, lung, and ovarian." (PMID 32264958, 2020). "ECM proteins Laminin-5, Tenascin-C, and Decorin bind EGFR to regulate its activation and function in cancers." (PMID 32719793, 2020). "Across the 18 cancers in their study, certain proteins stood out as pan-cancer markers such as THBS2, VCAN, SRRT, and TNC." (PMID 39698114, 2020). "TNC is highly expressed in the TME and the peptide containing the bioactive site of TNC, TNIIIA2, contributes to cancer aggression through β1-integrin activation both potently and persistently." (PMID 32708610, 2020). "Tenascin-C (TNC), a large extracellular matrix protein, is highly expressed in pathological contexts, especially in cancer." (PMID 31036754, 2019). "We identified several extracellular proteins as up‐regulated in invaded compared to noninvaded nerves (some of these were also seen in PNI compared to non‐PNI cancer), including laminins LAMA2, LAMB1, COL6A3, periostin (POST), nidogen 1 (NID1), and TNC." (PMID 30690892, 2019). "Overexpression of TNC induces ECM deposition, and aberrant activation of ECM-mediated signalling promotes cancer cell aggressiveness, and the epithelial-mesenchymal transition (EMT)." (PMID 28415821, 2017). "Tenascin C (TNC) a hexameric glycoprotein and periostin are ECM components that play crucial role in metastatic niche in mouse cancer models." (PMID 27486983, 2016). "In this study, we conducted simultaneous cancer biomarker imaging in three different cancer cell lines using two different QDs, QD605 and AD655, which are conjugated to tenascin-C aptamer (TTA-1) and AS1411 aptamer, respectively." (PMID 25871725, 2015). "The imaging of tenascin-C using QD-TTA-1 provided a consistent and high fluorescence signal in three different cancer cell lines." (PMID 25871725, 2015).